NLRP3 (NLR family pyrin domain containing 3)
Diseases named in the same sentence as NLRP3 in open-access papers (continued):
Sharing a sentence is not in itself a finding about the gene and the disease.
chronic kidney disease (continued). "Recently, it has been reported that NLRP3 inflammasome activation serves as a triggering mechanism leading to glomerular injury and ultimate end-stage renal disease (ESRD) under different pathological conditions." (PMID 31737627, 2019). "Our results demonstrate the critical role of nicotine in turning on inflammatory response via activating NLRP3 inflammasomes leading to renal inflammation and renal dysfunction during smoking and may help in understanding the pathophysiology of nicotine associated chronic kidney diseases." (PMID 31835256, 2019). "In this study, we show for the first time that a novel formulation of curcumin with improved bioavailability improves cardiac function by suppressing NLRP3 inflammasome activation and mature IL-1β release in rat model of chronic kidney disease." (PMID 28000751, 2016). "The inflammasome component Nlrp3 is constitutively expressed in the kidney and clearly enhanced following acute and chronic kidney disease (this study)." (PMID 24454932, 2014). "In a cohort of renal biopsies from patients with nondiabetic kidney disease, levels of mRNA encoding NLRP3 correlate with renal function, strongly suggesting that NLRP3 contributes to the pathogenesis of chronic kidney disease." (PMID 23843683, 2013). "Magnoflorine was found to promote Parkin/PINK1-mediated mitochondrial autophagy, thereby inhibiting NLRP3/Caspase-1-mediated pyroptosis, ultimately decreasing tubular cell steatosis, lipid deposition, tubular dilation, and glomerular fibrosis in chronic kidney disease." (PMID 40520024, 2025). "In contrast, clusters 0, 1, 6, and 7 primarily represented the major disease types investigated in the context of NLRP3 inflammasomes and cardiovascular disease, encompassing keywords such as coronary heart disease, metabolic syndrome, and chronic kidney disease." (PMID 39022620, 2024). "Chronic kidney disease (CKD) is caused by the convergence of fundamental mechanisms that underlie age-related tissue dysfunction, including chronic “sterile” NOD-like receptor protein-3 (NLRP3)-induced inflammation and cellular senescence." (PMID 37770948, 2023). "In 2010, it was shown that the gene expression of NLRP3 was significantly increased in nondiabetic patients with different causes of acute and chronic kidney diseases." (PMID 35204131, 2022). "NLRP3 is overexpressed in chronic kidney disease after I/R induced-acute renal injury." (PMID 36238294, 2022). "NLRP3 inflammasome promotes renal inflammation in chronic kidney diseases." (PMID 34858199, 2021). "Furthermore, studies have shown that NLRP3 activation has been implicated in an inflammasome complex which involves triggering the NF-κB pathway with release of IL-1β all of which may play a significant role in CaNL and eventually in the development of chronic kidney disease." (PMID 33802660, 2021). "The NLRP3 inflammasome is activated in both acute and chronic kidney disease." (PMID 32414157, 2020). "NLRP3 inflammasome activation is closely related to chronic kidney disease." (PMID 30807290, 2019). "We suggest that inflammasome-independent NLRP3 could be a therapeutic target of AKI to prevent the progression of chronic kidney disease." (PMID 30483252, 2018). "Expression of the NLRP3 inflammasome is enhanced in chronic kidney diseases." (PMID 28740332, 2017). "NLRP3 inflammasome activation by CtB may promote glomerular inflammation and other cell damages resulting into glomerular injury and end-stage renal disease." (PMID 29312937, 2017). "Overall, theracurmin, and other modulators of cardiac NLRP3 inflammasome, may present as novel therapeutic options for the treatment of cardiovascular events in the setting of chronic kidney disease." (PMID 28000751, 2016). "In chronic kidney disease (CKD) models, the myokine Irisin ameliorated palmitic acid-induced muscle atrophy by inhibiting fatty acid oxidation and the subsequent NLRP3 inflammasome activation and pyroptosis." (PMID 41334559, 2025).
chronic kidney disease (continued). "Recently, a study found that increased ROS production and NLRP3 activation leads to VC and pyroptosis in β-glycerophosphate treated VSMCs in chronic kidney disease (CKD)." (PMID 41335598, 2025). "Numerous investigations have additionally demonstrated the involvement of the NLRP3 inflammasome in the progression of chronic kidney diseases (CKD)." (PMID 38740765, 2024). "New evidence suggests that NLRP3 levels are considerably increased in the kidneys of chronic kidney disease (CKD) patients." (PMID 37624173, 2023). "Taken together, our findings suggest a significant role for the NLRP3 inflammasome in renal injury-induced cardiac dysfunction and presents inflammasome attenuation as a unique strategy to prevent adverse cardiac remodeling in the setting of chronic kidney disease." (PMID 28000751, 2016). "We show that theracurmin attenuates NLRP3 inflammasome activation in the heart and reduces circulating IL-1β levels, illustrating a cardio-protective effect of the compound and the potential therapeutic benefits of a theracurmin-based treatment strategy in the setting of chronic kidney disease." (PMID 28000751, 2016). "Finally, NLRP3 inflammasome pathway could turn to be a valuable therapeutic target to minimize or avoid severe clinical complications in chronic kidney disease patients with advanced renal impairment." (PMID 25798846, 2015). "Chronic inflammation and fibrosis are features of all forms of chronic kidney disease, including PKD, with NLRP3 inflammasome activation playing a central role." (PMID 39314240, 2024). "However, NLRP3 inhibition favors macrophage infiltration and/or macrophage reprogramming to a pro-inflammatory phenotype in models of chronic kidney disease (CKD) and pancreatic cancer." (PMID 37564649, 2023). "Indeed, inhibition at the terminal level of the NLRP3 inflammasome axis, IL-1β, with canakinumab (a monoclonal IL-1β antibody) reduced cardiovascular events in the recent CANTOS trial, but disturbingly also led to a loss in eGFR in subjects with chronic kidney disease." (PMID 35048962, 2022). "For example, our pervious study showed PT could effectively prevent chronic kidney disease (CKD) via autophagy to restraining TGF-β mediated NLRP3 inflammasome activation." (PMID 34983566, 2022). "The inhibition of ER stress, as well as Nlrp3 and ASC, suggests that redundant inflammatory pathways are involved in Aldo-induced chronic kidney disease." (PMID 27721575, 2016). "The level of NLRP3 protein in patients with chronic kidney disease (CKD) was higher than in patients without CKD at all time points." (PMID 39590595, 2024). "Research conducted in the past has revealed that NLRP3 of lupus nephritis and non-diabetic chronic kidney disease (CKD)in human are substantially upregulated." (PMID 33215255, 2021). "The NLRP3 inflammasome has been shown to contribute to many acute and chronic kidney diseases via canonical and noncanonical pathways that modulate apoptosis, inflammation, fibrosis and pyroptosis." (PMID 33917140, 2021). "NLRP3, IL-1β, and IL-18 are significantly upregulated in chronic kidney disease patients undergoing hemodialysis treatment, indicating that the NLRP3 inflammasome may be activated in and contribute to chronic inflammation in CKD." (PMID 32660446, 2020). "In particular, the NLRP3 (NACHT, LRR, and PYD domain-containing protein 3) inflammasome has been shown to cause acute and chronic kidney diseases by regulating canonical and noncanonical mechanisms of inflammation." (PMID 32410864, 2020). "Even though in general the data indicate that it would be beneficial to block the NLRP3 inflammasome, the CANTOS trial may have unmasked potential adverse effects as reflected by the worsening of kidney function among subjects with chronic kidney disease in particular in established disease." (PMID 35048962, 2022).
chronic kidney disease (continued). "Peripheral blood mononuclear cells (PBMCs) isolated from 11 HD patients and 14 volunteers without a history of chronic kidney disease, as well as macrophages with or without the uremic toxin indoxyl sulfate (IS) pretreatment, underwent canonical NLRP3 inflammasome induction." (PMID 33430226, 2021). "In one of these studies, it was shown that the absence of Nlrp3 led to a classical reduction of caspase-1 activation and maturation of IL-1β and IL-18 and diminished renal inflammation and injury in the late phase of experimental chronic kidney disease." (PMID 24454932, 2014). "This study evaluated the effectiveness of the NLRP3 inflammasome inhibitor MCC950 combined with ultrasound (US) and microbubbles (MBs) on kidney function and fibrosis in a rat model of chronic kidney disease (CKD)." (PMID 40822454, 2025). "This cross-sectional study of patients with chronic kidney disease (CKD) reveals that NLRP3 mRNA expression is higher in patients undergoing hemodialysis (HD) than in PD and non-dialysis CKD patients." (PMID 40725180, 2025). "Interestingly, in a model of chronic kidney disease, the expression of NLRP3 was linked to the control of TGF-β-dependent signaling although in our model enhanced TGF-β expressing cells were allied with absence of NLRP3 activation." (PMID 28740491, 2017). "Moreover, macrophages from chronic kidney disease (CKD) patients exposed to the uremic toxin IS displayed inflammation through activation of the AhR/NF–κB/MAPK cascade, in a process that induced the mature IL-1β production without activating NLRP3 inflammasome." (PMID 39211042, 2024).
colorectal cancer (124 papers, 2015 to 2025). A primary or metastatic malignant neoplasm that affects the colon or rectum. "NLRP3’s impact on tumorigenesis is complex, demonstrating both anti-tumorigenic effects, notably observed in colitis-associated colorectal cancer (CAC), and tumor-promoting effects, as seen in gastric and skin cancers." (PMID 41017127, 2025). "For instance, NLRP3 inflammasome-triggered pyroptosis enhances the effectiveness of anticancer agents in colorectal cancer, while decreased NLRP3 levels are linked to a poor prognosis in the disease." (PMID 40830103, 2025). "The pyrin domain-containing protein 3 [or NOD-like receptor protein 3 (NLRP3)] inflammasome and NLRP3 inflammasome have been associated with colorectal cancer formation." (PMID 38649928, 2024). "Polymorphisms and mutations in the NLRP3 gene have been implicated in various cancers, such as invasive colorectal cancer and pancreatic cancer." (PMID 38172822, 2024). "In colorectal cancer, NLRP3 inflammasome activation is associated with natural killer cells recruitment and tumour suppression." (PMID 39595195, 2024). "The Q705K SNP in NLRP3 is associated with higher inflammasome activation and poor patient survival in advanced stage colorectal cancer." (PMID 35499706, 2022). "In this line, a single-nucleotide polymorphism in Nlrp3 gene Q705K (rs35829419) was correlated with decreased survival in colorectal cancer patients and was also mapped at high frequency in patients with pancreatic cancer." (PMID 36032139, 2022). "Several studies have reported that NLRP3 inflammasome-deficient models correlate with an increase in the risk of colorectal cancer." (PMID 34571825, 2021). "A heterozygous NLRP3 (Q705K) mutation has also been shown to be associated with a poor outcome in patients with advanced colorectal cancer." (PMID 34457117, 2021). "Galloflavin can inhibit the malignant behavior of colorectal cancer cells in the inflammatory microenvironment by targeting NLRP3, which is an important mechanism underlying the inhibitory effect of galloflavin on colorectal cancer progression." (PMID 34955826, 2021). "Nlrp3−/−, Nlrp6−/−, Nlrc4−/−, Nlrp1−/−, Nlrx1−/− and Nlrp12−/− mice show increased susceptibility to inflammation-induced colorectal cancer as compared to wild-type mice." (PMID 31186453, 2019). "Evidence of NLRP3 inflammasome in suppressing hepatic tumor growth comes from the study showing that colorectal cancer (CRC) metastatic liver tumor burden is exacerbated in NLRP3-deficient mice." (PMID 30319645, 2018). "Recently, genome-wide association studies have linked single nucleotide polymorphisms in the gene encoding NLRP3 with increased susceptibility to Crohn's disease as well as with poor survival rate for colorectal cancer." (PMID 30619282, 2018). "Similar to that, the colchicine could modulate the NLRP3 inflammasome among the female, leading to colchicine users being associated with the lower aHR for colorectal cancer." (PMID 38649928, 2024). "Moreover, The NLRP3 inflammasome mediates pyroptosis, which inhibits tumor development in colorectal cancer (CRC) or colitis-associated cancer which is a major complication of inflammatory bowel diseases." (PMID 37715239, 2023). "More and more studies have shown that NLRP3 inflammasome was closely associated with the progression of various tumors (such as gastric cancer, colorectal cancer, liver cancer, etc.)." (PMID 36619871, 2022). "In the tumor-bearing mouse model of colorectal cancer, we found that Gal could cause tumor tissue damage and inhibit the expression of NLRP3 and ASC in the tumor, which were consistent with the results in SW480 cells." (PMID 34955826, 2021).
colorectal cancer (continued). "Interestingly, in NLRP3 deficiency conditions, there is a significant decrease in the IL-18 level in the intestine with a pronounced antitumor effect in colorectal cancer." (PMID 34885171, 2021). "In addition, NLRP3 inflammasome deficiency seems to cause increased tumor burdens in colorectal cancer." (PMID 32733479, 2020). "Other evidence for instance activation of NLRP3 in kupffer cells inhibited colorectal cancer liver metastasis by releasing IL‐18 and promoting maturation of hepatic NK cells." (PMID 40671401, 2025). "In this regard, the ability of NLRP3 to protect against the development of colorectal cancer is attributed to the effector function of caspase-1 to mediate the secretion of IL-18." (PMID 40227443, 2025). "NLRP3 inflammasome activation in macrophages has been shown to drive colorectal cancer metastasis to the liver." (PMID 40848148, 2025). "Alu RNA induces epithelial-to-mesenchymal transition in colorectal cancer via NLRP3 inflammasome activation and IL-1β release." (PMID 40565315, 2025). "Alu RNA induces epithelial-to-mesenchymal transition in colorectal cancer via NLRP3 inflammasome activation and IL-1β release, while BC200 promotes EBV-associated nasopharyngeal carcinoma by sequestering miR-6834-5p to upregulate thymidylate synthase." (PMID 40565315, 2025). "For example, mice deficient in Nlrp3 or other inflammasome components are more susceptible to colon tumors following AzOxyMethane/Dextran Sodium Sulfate treatment, suggesting a protective role of the NLRP3 inflammasome in colorectal cancers." (PMID 40195474, 2025). "Elevated NLRP3 expression is elevated in several cancer types, such as colorectal carcinoma (CRC), oral squamous cell carcinoma (OSCC), and non-small cell lung cancer (NSCLC)." (PMID 40692785, 2025). "MiR-495-3p inhibited LPS-induction of NLRP3 inflammasome in vitro and vivo, and miR-370-3p can modulate inflammatory responses during epithelial-mesenchymal transition in colorectal cancer." (PMID 39200160, 2024). "In colorectal cancer, the role of NLRP3 remains controversial, in terms of both protection against tumorigenesis and promoting colorectal carcinogenesis by causing tumor cells to migrate faster." (PMID 38182564, 2024). "FL118, a novel camptothecin anticancer drug, is found to inhibit the growth and metastasis of colorectal cancer through the NLRP3-ASC-Caspase-1 pathway by mediating the pyroptosis of SW480 and HT29 cells." (PMID 38654314, 2024). "Here, we showed that Alu RNA can induce epithelial-to-mesenchymal transition (EMT) through NLRP3 inflammasome activation and IL-1β release in colorectal cancer (CRC) cells." (PMID 38486106, 2024). "In the future, we want to continue to elucidate the mechanism of action and outcome of NLRP3 in colorectal cancer and determine more mechanisms of action and signal transduction pathways between NLRP3 and other digestive system diseases." (PMID 38182564, 2024). "Macrophage STING signaling pathway promoted NLRP3 inflammasome activation, enhanced anti-tumor function of NK cells, and inhibited liver metastasis from colorectal cancer." (PMID 38195584, 2024). "When NLRP3 was downregulated in colorectal cancer cells, a reduction in cell migration and invasion was noted." (PMID 38317229, 2024). "STING signaling is known to promote the production of interleukin-18 and IL-1β by macrophages through activation of NLRP3, mediating the anti-tumor function of NK cells to eliminate colorectal cancer liver metastases." (PMID 39325798, 2024). "In colorectal cancer, NLRP3-positive patients had a poor prognosis, and its expression level is closely related to prognosis." (PMID 37715239, 2023). "In a separate report, macrophages were found to promote the metastatic progression of colorectal cancer through mechanisms dependent on the activity of the NLRP3 inflammasome." (PMID 37885032, 2023).